INS (insulin)
Diseases named in the same sentence as INS in open-access papers (continued):
Sharing a sentence is not in itself a finding about the gene and the disease.
psoriasis (continued). "Experiments have shown that serum insulin levels and the insulin resistance index are positively correlated with the severity of psoriasis." (PMID 34372872, 2021). "The identification of multiple metabolism related pathways such as BCAA, lipid, and insulin signaling supports the observed correlation between psoriasis and metabolic disorders." (PMID 30642337, 2019). "It has been shown that the use of an insulin stimulating agent (glucagon like peptide 1—GLP-1) can improve psoriasis emphasizing the effect of insulin resistance in inflammation." (PMID 29483947, 2018). "And type 1 diabetics who also develop psoriasis have reported lowering their insulin dose after starting treatment for psoriasis." (PMID 30474082, 2018). "With further evaluation in clinical studies, Insulin sensitizers can be used for the management of psoriasis patients with MS." (PMID 27531132, 2016). "Insulin sensitizers have shown improvement in the parameters of MS as well as disease severity in psoriasis patients." (PMID 27531132, 2016). "As in the case of infliximab, there is no data analyzing the relation betweenthe use of adalimumab and the change in insulin sensitivity or in glucoselevels in patients with psoriasis." (PMID 28099601, 2016). "In particular, thiazolidinediones, a novel class of insulin-sensitizing drugs, have demonstrated promise for treatment of psoriasis." (PMID 25977937, 2015). "The frequency of self-monitoring of blood glucose per week was significantly higher in psoriasis patients, even after additional adjustment for insulin use (14.8 [13.4; 16.2] versus 12.9 [12.9; 13.0] SMGB per week, p = 0.008)." (PMID 26357664, 2015). "In two small studies, psoriasis patients treated with etanercept demonstrated a decrease in fasting serum insulin levels." (PMID 23843781, 2013). "As such, it can be said that adipokines play a crucial role in the relationship between obesity, psoriasis, and nonalcoholic fatty liver disease (NAFLD); adiponectin, a hormone that promotes insulin sensitivity and fatty acid oxidation, is closely associated with both psoriasis and NAFLD." (PMID 40731925, 2025). "In glucose-tolerant individuals, moderate to severe psoriasis has been linked to a marked reduction in insulin sensitivity when compared with non-psoriatic counterparts." (PMID 40806666, 2025). "The chronic inflammation inherent in psoriasis leads to the activation of immune cells and the release of cytokines that disrupt insulin signaling pathways, mainly through the serine phosphorylation of insulin receptor substrate-1 (IRS-1), thereby promoting insulin resistance." (PMID 40277935, 2025). "The investigators observed that PsO-iPSCs-derived keratinocytes exhibited dysregulated transcripts associated with psoriasis, keratinocyte differentiation, as well as insulin resistance, providing further evidence of keratinocyte abnormalities driving psoriasis pathology." (PMID 38720903, 2024). "Previous data reported that normal glucose-tolerant patients with moderate to severe psoriasis were more insulin-resistant compared to controls suggesting that psoriasis may represent a pre-diabetic condition." (PMID 33834030, 2021). "Stopping insulin and reintroducing metformin led to the remission of psoriasis." (PMID 33808460, 2021). "On the other hand, patients who have a history of insulin treatment, although frequent users of metformin, do not have a lower risk of psoriasis." (PMID 33808460, 2021). "Insulin sensitivity is reportedly deregulated in individuals who have psoriasis based on their leptin and adiponectin levels, which regulate insulin sensitivity/activity through the inflection of insulin signaling and the molecules associated with glucose and lipid metabolism." (PMID 34203830, 2021). "Besides immune related processes, pathways such as lipid metabolism, insulin signaling, adipokine signaling, collagen formation, and cell-cell communication were also found to be enriched for psoriasis EWAS signals." (PMID 30642337, 2019).
psoriasis (continued). "Insulin therapy was significantly more frequent in patients with psoriasis (p = 0.001)." (PMID 26357664, 2015). "Psoriasis is currently considered a “T-cell mediated disease”, and shares a common immune profile with MetS, both of them having increased Th type 1 proinflammatory cytokines, with a wide range of actions: on insulin signaling, lipid metabolism, adipogenesis." (PMID 25713604, 2014). "In addition, since miR-33 is involved in the posttranscriptional regulation of genes associated with lipid metabolism, one study reported that the plasma levels of lipid and glucose metabolism-related miR-33 are increased and correlated with insulin in psoriasis patients." (PMID 32411787, 2020). "Furthermore, patients with PsA and psoriasis share some other pathophysiological characteristics (neoangiogenesis, insulin uptake, adipogenesis, lipid metabolism, and immune and epidermal proliferation) and genetic aspects, such as peroxisome proliferator activated receptor (PPAR) polymorphism." (PMID 32028959, 2020). "Moreover, psoriasis patients also showed altered levels of further adipokines such as visfatin and resistin both of which have metabolic functions, also playing an important role in insulin sensitivity." (PMID 25977937, 2015). "This may be probably due to reduced insulin sensitivity in psoriasis patients." (PMID 26357664, 2015). "Moreover, insulin sensitivity indices were reported to be significantly lower in psoriatics, as compared with controls, with serum insulin level and IR indices demonstrating a significant positive correlation with the severity of psoriasis and being decreased after systemic treatments." (PMID 25977937, 2015). "The levels of fasting glucose, insulin, IGFBP3, and IGFBP6 were higher in patients with psoriasis, while the levels of IGF-1, IGF-1R, and IGBP4 were higher in controls." (PMID 41635444, 2026). "The levels of NFL, tau, and insulin and the HOMA‐IR values remained significantly increased in the patients with psoriasis compared to those in controls upon stratification by age, gender, BMI, and smoking status." (PMID 32896023, 2021). "Mean homeostasis model assessment (HOMA‐IR) values (6.82 vs 3.25) and serum levels of insulin (28.19 vs 15.71), NFL (5.74 vs 1.98), and tau (348.17 vs 207.30) in patients with psoriasis were found to be significantly higher than those of in healthy controls." (PMID 32896023, 2021). "Mean serum insulin level and HOMA-IR index in the psoriasis group (4.79 ± 3.46 and 0.99 ± 0.70, resp)." (PMID 25587268, 2014). "In fact, these results demonstrate that in healthy conditions, insulin is able to regulate cell proliferation and differentiation of keratinocytes with protein kinases, PI3-K protein and kinase B. In psoriasis, IL-1β is found in large quantities in the dermis." (PMID 23935446, 2013). "Outside of the hospital, insulin therapy effectively maintained stable blood glucose levels, and there were no further episodes of psoriasis flare-ups." (PMID 37960733, 2023). "The A allele was identified to be the “risk allele” related to not only elevated BMI and hip and waist circumference measurements, but also to a higher PASI index (Psoriasis Area Severity Index), CRP (C-reactive protein) values, and serum insulin concentrations." (PMID 35806402, 2022). "The increased levels of inflammatory cytokines also have an impact on insulin secretion and resistance, though no clear correlation between psoriasis and glucose levels was found in the Norwegian study in 2018." (PMID 32512854, 2020). "A recent study on 29 non-diabetic individuals with moderate-to-severe psoriasis disclosed a statistically significant improvement of insulin sensitivity after 6 months of adalimumab therapy." (PMID 26633680, 2015). "No significant changes in insulin sensitivity or in the levels of fasting blood glucose were seen in a study in 18 patients with psoriasis after 12 weeks of treatment with adalimumab." (PMID 25654080, 2015).
psoriasis (continued). "Insulin therapy was used significantly more often in T2D patients with comorbid psoriasis, while nonpharmacological therapy was less common." (PMID 26357664, 2015). "Accordingly, the reduction in resistin levels was maintained 3 mo after retinoid treatment in males with psoriasis, unlike the transient effect found by the authors on insulin sensitivity." (PMID 17479165, 2007). "Whether this is dependent on or independent of insulin desensitisation, it can further enhance metabolic syndrome and skin inflammation in psoriasis." (PMID 34372872, 2021). "For example, the BCAA biosynthesis/catabolism processes are unique to GWAS, whereas platelet and coagulation, insulin signaling, and lipid metabolism pathways appear to be more specific to EWAS, suggesting that genetic and environmental factors also perturb different pathways leading to psoriasis." (PMID 30642337, 2019). "In keeping with that, we previously observed a significant improvement (p = 0.008) of insulin sensitivity after 6 months of adalimumab therapy (QUICKI at baseline: 0.35 ± 0.04 versus 0.37 ± 0.04 at month 6) in our series of nondiabetic patients with moderate-to-severe psoriasis." (PMID 27293954, 2016). "It seems to be no deleterious influence of the drug on lipid profile ofpatients with psoriasis according to the studies, although none of these hasbeen specifically designed for the observation of this event, but rather todetermine increase of BMI and insulin tolerance in psoriaticpatients." (PMID 28099601, 2016).
hyperthyroidism (85 papers, 2006 to 2026). Overactivity of the thyroid gland resulting in overproduction of thyroid hormone and increased metabolic rate. "Hyperthyroidism is associated with an increased level of postprandial plasma insulin and proinsulin but also with an increased apoptosis of pancreatic β cells." (PMID 37628857, 2023). "Insulin sensitivity was significantly decreased in patients with subclinical hyperthyroidism, thereby increasing the risk of cardiovascular events." (PMID 29081800, 2017). "However, there is also evidence that overt and subclinical hyperthyroidism have been associated with increased hepatic gluconeogenesis, increased insulin clearance and resistance, providing a plausible justification for a U-shaped curve." (PMID 37988662, 2023). "Hyperthyroidism has also been associated with enhanced insulin sensitivity." (PMID 23671867, 2013). "Meanwhile, in hyperthyroidism, the insulin signaling pathway is impaired, leading to insulin resistance and suspension of hepatic glucose." (PMID 40166517, 2025). "TD2M exhibits a unique pathophysiological signature, characterised by disrupted insulin secretion, altered glucose handling, and heightened catecholamine levels, which synergise to promote hyperthyroidism." (PMID 41210054, 2025). "For example, no cases of dilated cardiomyopathy were observed in the subgroup of insulin-treated patients with hyperthyroidism, but the small size of this group (n = 54) limits the generalizability and interpretability of this finding." (PMID 41153651, 2025). "In hyperthyroidism, there is an increase in the glomerular filtration rate, which leads to increased excretion of insulin and hence decreased insulin levels, aggravating DKA." (PMID 38966457, 2024). "Increased β-adrenergic activity and insulin secretion induced by hyperthyroidism can additionally contribute to an increase in Na+-K+-ATPase expression." (PMID 39188503, 2024). "Due to an accelerated rate of degradation and a significant release of physiologically inactive insulin precursors, hyperthyroidism reduces the half-life of insulin." (PMID 36983604, 2023). "Insulin-stimulated glucose oxidation rate increases in muscle and adipose tissue of patients with hyperthyroidism." (PMID 38004062, 2023). "In instances of hypo- and hyperthyroidism, THs possess the capacity to regulate insulin secretion both directly and indirectly, through the suppression of glucose-induced insulin secretion and the reduction of β-cell responsiveness." (PMID 37946276, 2023). "It is known that overproduction of THs can affect the alternation of insulin signaling and glucose metabolism, and clinical and experimental hyperthyroidism often coincides with impaired glucose tolerance." (PMID 37946276, 2023). "We investigate the disturbed glucose-insulin dynamics for patients under two different progression rates of hyperthyroidism." (PMID 36619543, 2022). "The altered glucose-insulin dynamics of hyperthyroid patients after the administration of anti-thyroid drugs were analyzed upon the proposed drug-treatment model for hyperthyroidism." (PMID 36619543, 2022). "The aim of this study was to assess the effect of hyperthyroidism and its treatment on body weight and composition, insulin resistance, and mediators of appetite and energy homeostasis, namely ghrelin, leptin, adiponectin, and FGF21." (PMID 35929907, 2022). "In situations of hyperthyroidism, there is a resistance to insulin status, probably due to increased expression of CPT-1 and reduced malonyl-CoA." (PMID 35893242, 2022). "Graves’ thyrotoxicosis is a condition believed to lead to an insulin-resistant state, and hence adiponectin levels would theoretically be lower in hyperthyroidism." (PMID 35894647, 2022). "Another postulated mechanism is that during hyperthyroidism, the half-life of insulin is reduced, the degradation of insulin is heightened, and biologically inactive proinsulin is released." (PMID 33602219, 2021).
hyperthyroidism (continued). "As insulin-stimulated rates of glycogen synthesis are reduced in muscle during hyperthyroidism, glucose residues are utilized by glycolysis and converted to glucose-6-phosphate catalyzed by hexokinases (HKs)." (PMID 34675885, 2021). "An independent report has also indicated that patients with overt or subclinical hyperthyroidism exposed to a glucose tolerance test have higher circulating levels of glucose and insulin." (PMID 33048427, 2020). "A survey showed a dual β cell defect in hyperthyroidism patients: decreased insulin release in response to hyperglycemia and increased proinsulin levels both in the fasting state and in response to a meal." (PMID 30013597, 2018). "For instance, hyperthyroidism leads to impaired insulin secretion, which suppresses hepatic glucose production and promotes glucose uptake in the muscle." (PMID 29783969, 2018). "Nevertheless excluding patients with hyperthyroidism still showed a significant difference in the insulin-free period between the groups." (PMID 24580798, 2014). "After excluding all patients with hyperthyroidism from the analysis, the difference regarding the insulin-free period between the groups remained statistically significant (p = 0.002)." (PMID 24580798, 2014). "In hyperthyroidism, thyroid hormone can antagonize insulin action on the liver leading to increased hepatic glucose output by the sympathetic pathway from the hypothalamus and transcriptional regulation of metabolic genes." (PMID 24872812, 2014). "In hyperthyroidism, endogenous glucose production is elevated and reduces hepatic insulin sensitivity in humans due to glycogenesis and glycogenolysis." (PMID 23671867, 2013). "The increase in the glomerular filtration rate in hyperthyroidism leads to an increased insulin clearance and hence a decreased insulin level." (PMID 21492449, 2011). "In hyperthyroidism, decreased, normal, or even increased levels of plasma insulin have been reported." (PMID 21941681, 2011). "T3 and T4, along with thyroid peroxidase antibody (TPOAb), can, directly and indirectly, regulate insulin secretion either by reducing glucose-induced insulin secretion or by reducing beta-cell responsiveness that results in hypo- and hyperthyroidism, respectively." (PMID 40076791, 2025). "In addition, the half-life of insulin is reduced by an increased rate of degradation in diabetic patients with hyperthyroidism." (PMID 40563510, 2025). "The differential correlations of FT4 and T3 with insulin sensitivity may seem complex and reflect inconsistencies within the literature regarding the impact of hyperthyroidism on insulin sensitivity and glucose tolerance." (PMID 39203787, 2024). "Furthermore, increased insulin degradation and accelerated insulin clearance are observed in individuals with hyperthyroidism." (PMID 38004062, 2023). "However, in hyperthyroidism, insulin clearance is increased due to the response of β cells to glucose or increased catecholamines." (PMID 37627914, 2023). "Severe hyperthyroidism may influence the secretion of insulin, increase gluconeogenesis, and affect carbohydrate metabolism, leading to hyperglycemia." (PMID 37519546, 2023). "Increased secretion of insulin and elevated fasting insulin are observed in hyperthyroidism." (PMID 36619543, 2022). "The aim of this study was to assess the effect of hyperthyroidism and its treatment on body weight and composition, insulin resistance, and mediators of appetite and energy homeostasis, namely ghrelin, leptin, adiponectin, and fibroblast growth factor 21 (FGF21)." (PMID 35929907, 2022). "Lenzen at al had showed that, in rat pancreas, lower TSH (experimental hyperthyroidism) could decrease insulin secretion." (PMID 34106595, 2021). "Insulin resistance of hepatic and peripheral tissues occurs in hyperthyroidism." (PMID 27193069, 2016). "However, in humans, FGF21 serum levels were unaltered in hyperthyroidism, as were insulin and glucose levels." (PMID 25172631, 2014).